NHLRC2 (NHL repeat containing 2)
Description:
Required for normal embryonic development.
Synonyms: FLJ25621; FLJ20147; FLJ33312; MGC45492; DKFZp779F115; FINCA
Tractability: Antibody: its Gene Ontology location is reachable by antibodies, with high confidence. PROTAC: ubiquitination databases record sites on it; its protein half-life has been measured.
Gene: Protein-coding gene on chromosome 10 (113,854,475 to 113,917,194, forward strand). Ensembl gene ENSG00000196865.
Subcellular location: Cytoplasm, cytosol
Subcellular location (Human Protein Atlas): Nucleoplasm
Pathways (Reactome):
Hemostasis: Platelet degranulation
Gene Ontology:
Molecular function: protein binding
Cellular component: cytosol; extracellular region; platelet alpha granule lumen
Genetic constraint (gnomAD): Loss-of-function variants: 15 observed, 31.92 expected, observed/expected ratio (o/e) 0.47, 90% interval 0.31 to 0.72. The upper end of that interval is the gene's LOEUF score, 0.72, which puts it in group 2 of 6, group 1 being the genes least tolerant of losing a copy. Missense variants: 456 observed, 501.69 expected, observed/expected ratio (o/e) 0.91, 90% interval 0.84 to 0.98. Synonymous variants: 194 observed, 189.06 expected, observed/expected ratio (o/e) 1.03, 90% interval 0.91 to 1.16.
Homologues: Orthologues: chimpanzee NHLRC2 (99% identical), macaque NHLRC2 (97% identical), dog NHLRC2 (91% identical), pig NHLRC2 (90% identical), guinea pig NHLRC2 (89% identical), rabbit NHLRC2 (88% identical), mouse Nhlrc2 (84% identical), rat Nhlrc2 (77% identical), tropical clawed frog nhlrc2 (65% identical), zebrafish nhlrc2 (61% identical), Drosophila melanogaster CG12547 (38% identical).
Diseases named in the same sentence as NHLRC2 in open-access papers:
NHLRC2 is named in the same sentence as 37 diseases in open-access papers, as found by Europe PMC text mining. Sharing a sentence is not in itself a finding about the gene and the disease. The quoted sentences say what the papers report.
Alzheimer disease (4 papers, 2020 to 2023). A progressive, neurodegenerative disease characterized by loss of function and death of nerve cells in several areas of the brain leading to loss of cognitive function such as memory and language. "Altered NHLRC2 protein and gene expression levels have been detected in neurodegenerative diseases such as Parkinson and Alzheimer’s disease; however, publications on the role of NHLRC2 in MS are still lacking." (PMID 37559720, 2023). "In addition, altered NHLRC2 and NHLRC2 mRNA levels have been detected in neurodegenerative diseases such as Parkinson’s disease (PD) and Alzheimer’s disease (AD)." (PMID 33297935, 2020).
FINCA syndrome (4 papers, 2022 to 2025). "So far, only 17 variants from 29 patients of NHLRC2 have been identified to be associated with FINCA syndrome." (PMID 39328589, 2024). "Fibrosis, neurodegeneration, and cerebral angiomatosis (FINCA) syndrome is an autosomal recessive genetic disorder caused by mutations in NHL-repeat-containing protein 2 (NHLRC2) gene." (PMID 39328589, 2024). "This case report describes two Chinese siblings with FINCA syndrome carrying a novel frameshift variant, c.1610dupT (p.L537Ffs*17), of NHLRC2 gene." (PMID 39328589, 2024). "The patient in this study had MCID due to a novel homozygous mutation in NDUFS6 and FINCA syndrome due to a novel compound heterozygous mutation in NHLRC2." (PMID 35801790, 2022). "The molecular pathogenic mechanism involved in FINCA syndrome induced by NHLRC2 deficiency remains to be studied." (PMID 35801790, 2022). "The patient has MCID due to a novel mutation in NDUFS6 and FINCA syndrome due to novel mutations in NHLRC2, which is the main reason for the rapid onset and quick death of the patient." (PMID 35801790, 2022). "We report two Chinese siblings with FINCA syndrome carrying a novel variant of NHLRC2 gene." (PMID 39328589, 2024). "Fibrosis, neurodegeneration, and cerebral angiomatosis (FINCA) syndrome, an autosomal recessive disorder caused by a variant of the NHL-repeat-containing protein 2 (NHLRC2) gene, characterized by interstitial lung fibrosis, neurodegeneration, and cerebral angiomatosis." (PMID 39328589, 2024). "So we speculated that the compound heterozygous mutation carried by the patient resulted in abnormal NHLRC2 gene function and triggered FINCA syndrome." (PMID 35801790, 2022). "FINCA syndrome is a recently discovered monogenetic disease related to NHLRC2 dysfunction." (PMID 39328589, 2024). "The pathogenic mechanisms leading to the clinical manifestations of ILD/lung fibrosis and neurodegeneration in FINCA syndrome caused by NHLRC2 deficiency have not yet been fully elucidated." (PMID 39328589, 2024).
idiopathic pulmonary fibrosis (4 papers, 2022 to 2025). Idiopathic pulmonary fibrosis (IPF) is a nonneoplastic pulmonary disease that is characterized by the formation of scar tissue within the lungs in the absence of any known cause. "FINCA patients often develop pulmonary fibrosis and increased NHLRC2 expression has been shown to associate with idiopathic pulmonary fibrosis." (PMID 40510178, 2025). "More information on the temporal changes in both cytokine response and fibrogenesis of FINCA mice is needed to fully understand the role of the NHLRC2 in pulmonary fibrosis." (PMID 40510178, 2025). "NHLRC2 has been previously flagged in a study as a differentially expressed gene when comparing rapidly and slowly progressing idiopathic pulmonary fibrosis (IPF) patients." (PMID 39328589, 2024). "Variants of NHL repeat-containing protein 2 (NHLRC2) have been associated with severe fibrotic interstitial lung disease in early childhood and NHLRC2 has been listed as a differentially expressed gene between rapidly and slowly progressing idiopathic pulmonary fibrosis (IPF) patients." (PMID 35964085, 2022).
colon cancer (3 papers, 2017 to 2024). "Downregulation of NHLRC2 has been shown to increase the susceptibility of human colon cancer cells to reactive oxygen species (ROS)–induced apoptosis." (PMID 39328589, 2024). "Taken together, these results suggest that excess ROS production causes a caspase-8-mediated decrease in NHLRC2 protein levels, leading to apoptotic cell death in colon cancer cells, indicating an important role for NHLRC2 in the regulation of ROS-induced apoptosis." (PMID 29242562, 2017). "Excess reactive oxygen species (ROS) production led to a caspase-8-mediated decrease in NHLRC2 protein levels, leading to apoptotic cell death in colon cancer cells, suggesting an important role for NHLRC2 in the regulation of ROS-induced apoptosis." (PMID 37179546, 2023). "Here we show that the NHL-repeat-containing protein 2 (NHLRC2) thioredoxin-like domain protein is cleaved by caspase-8 in ROS-induced apoptosis in the HCT116 human colon cancer cell line." (PMID 29242562, 2017). "In this study, we report that NHLRC2 is cleaved by caspase-8 in ROS-induced apoptosis in the HCT116 human colon cancer cell line." (PMID 29242562, 2017).
Intellectual disability (2 papers, 2023). "The clinical and histopathological characteristics of NHLRC2-related diseases, namely fibrosis, infection susceptibility/immunodeficiency/intellectual disability, neuro-developmental disorder/neurodegeneration, and chronic anemia/cerebral angiomatosis can be summarized by the acronym FINCA." (PMID 37179546, 2023). "Taken together, our findings broaden the known phenotypic and molecular spectrum and emphasize that NHLRC2-related disease should be considered in patients presenting with intellectual disability, movement disorders, neuroregression and epilepsy with or without pulmonary involvement." (PMID 37188825, 2023).
lung adenocarcinoma (2 papers, 2023 to 2025). A carcinoma that arises from the lung and is characterized by the presence of malignant glandular epithelial cells. "A high level of NHLRC2 has been associated with shortened survival in lung adenocarcinoma, a type of non-small-cell lung cancer." (PMID 40510178, 2025).
arbovirus infection (1 paper, 2026). A viral infection that is transmitted by an arthropod. "Therefore, targeting C3PO or NHLRC2 would be considered as a promising strategy in controlling arbovirus infection." (PMID 41173802, 2026).
autism spectrum disorder (1 paper, 2025). A spectrum of developmental disorders that includes autism, and Asperger syndrome. "For example, in one recent publication, NHLRC2 was found to correlate with a behavioural subtype of autism spectrum disorder." (PMID 40510178, 2025).
Autoimmunity (1 paper, 2024). The occurrence of an immune reaction against the organism's own cells or tissues. "Although the physiological function of NHLRC2 is not yet fully elaborated, previous studies have demonstrated that the possible pathogenic mechanism of NHLRC2 is associated with inflammation or autoimmunity." (PMID 39328589, 2024).
chronic asthma (1 paper, 2024). An asthma that is characterized by the development of persistent airway inflammation and recurrent attacks of breathlessness and wheezing, which vary in severity and frequency. "In addition, NHLRC2 expression was found to increase under inflammatory conditions in an equine model of chronic asthma." (PMID 39328589, 2024).
epilepsy (1 paper, 2023). A brain disorder characterized by episodes of abnormally increased neuronal discharge resulting in transient episodes of sensory or motor neurological dysfunction, or psychic dysfunction. "Taken together, our data broaden the hitherto known phenotypic spectrum, extend the allelic series and emphasize that rare biallelic NHLRC2 variants should be considered relevant in patients with NDD/ID, movement disorders, neuroregression and epilepsy even in the absence of pulmonary findings." (PMID 37188825, 2023).
Granuloma (1 paper, 2025). A compact, organized collection of mature mononuclear phagocytes, which may be but is not necessarily accompanied by accessory features such as necrosis. "Despite the significant decrease in NHLRC2 in the FINCA mouse lungs, we have not observed any abnormalities in the tissue histology or signs of granuloma-like lesions and fibrosis." (PMID 40510178, 2025).
Infertility (1 paper, 2022). "Further studies on this gene will determine the molecular pathways affected by NHLRC2 to reveal its potential role in early post implantation development and infertility." (PMID 35258166, 2022).
lung disease (1 paper, 2023). "We observed a correlation of remaining NHLRC2 protein levels with phenotype severity: higher reduction in total NHLRC2 protein level correlated with more severe phenotypes, ranging from milder over more severe neurological symptoms to additional lung disease." (PMID 37188825, 2023).
macrocytic anaemia (1 paper, 2025). "Recently, NHLRC2 has been associated with human erythroid development, which would explain the haemolytic macrocytic anaemia described in FINCA patients." (PMID 40510178, 2025).
respiratory failure (1 paper, 2023). The significant impairment of gas exchange within the lungs resulting in hypoxia, hypercarbia, or both, to the extent that organ tissue perfusion is severely compromised. "In total, 11 out of 13 individuals with NHLRC2-related disease showed respiratory symptoms and six died of respiratory failure before the age of three years." (PMID 37188825, 2023).
Salmonella Infections (1 paper, 2019). Infections with bacteria of the genus SALMONELLA. "Since nothing was known about the biological function of NHLRC2 in Salmonella infection, it was chosen for study in greater detail." (PMID 31594818, 2019). "An NHLRC2 mutant exhibited strong (>85%) resistance to Salmonella infection." (PMID 31594818, 2019).
Sepsis (1 paper, 2023). Sepsis is defined as life-threatening organ dysfunction caused by a dysregulated host response to infection. "In our study, we constructed a machine learning model using five genes, including GTPBP2, ALDOA, PRKAR2A, KIF2C, and NHLRC2, to identify sepsis patients with a poor prognosis." (PMID 38054005, 2023). "In our investigation, we identified GTPBP2, ALDOA, PRKAR2A, NHLRC2, and KIF2C as genes related to sepsis death using three distinct techniques." (PMID 38054005, 2023).
cancer (3 papers, 2017 to 2021). A tumor composed of atypical neoplastic, often pleomorphic cells that invade other tissues. "The hub genes (PIK3CA, STRN, C9orf102, REST, and NHLRC2) obtained from LinkedOmics were submitted to GSCALite for cancer pathway activity and drug sensitivity analysis." (PMID 34367282, 2021). "Therefore, NHLRC2 may be a possible drug target to sensitize cancer cells to ROS-dependent apoptosis induced by cancer chemotherapy." (PMID 29242562, 2017). "Moreover, we also conducted cancer pathway activity and drug sensitivity analysis of hub genes (PIK3CA, STRN, C9orf102, REST, and NHLRC2) obtained from LinkedOmics." (PMID 34367282, 2021).
NHLRC2 also shares sentences with these, for which no sentence is quoted: Parkinson disease (4 papers); neurodegenerative disease (3); movement disorder (2); muscular atrophy (2); Ataxia (1); developmental delay (1); Dystonia (1); Immunodeficiency (1); infection (1); interstitial lung disease (1); lung carcinoma (1); non-small cell lung carcinoma (1); Parkinson (1); rectal cancer (1); scoliosis (1); Skeletal muscle atrophy (1); sporadic amyotrophic lateral sclerosis (1); Strabismus (1).